H2BC3 (H2B clustered histone 3)
Description:
Core component of nucleosome. Nucleosomes wrap and compact DNA into chromatin, limiting DNA accessibility to the cellular machineries which require DNA as a template. Histones thereby play a central role in transcription regulation, DNA repair, DNA replication and chromosomal stability. DNA accessibility is regulated via a complex set of post-translational modifications of histones, also called histone code, and nucleosome remodeling.
Synonyms: H2B/f; H2BFF; HIST1H2BB; H2B.1
Tractability: Small molecule: a structure with a bound ligand is known. PROTAC: UniProt records ubiquitination sites on it; ubiquitination databases record sites on it.
Gene: Protein-coding gene on chromosome 6 (26,042,771 to 26,043,713, reverse strand). Ensembl gene ENSG00000276410.
Subcellular location: Nucleus; Chromosome
Subcellular location (Human Protein Atlas): Nucleoplasm; Cytosol
Pathways (Reactome):
Gene expression (Transcription): B-WICH complex positively regulates rRNA expression; DNA methylation; ERCC6 (CSB) and EHMT2 (G9a) positively regulate rRNA expression; MLL4 and MLL3 complexes regulate expression of PPARG target genes in adipogenesis and hepatic steatosis; NoRC negatively regulates rRNA expression; PRC2 methylates histones and DNA; RNA Polymerase I Promoter Escape; RNA Polymerase I Promoter Opening; RUNX1 regulates genes involved in megakaryocyte differentiation and platelet function; RUNX1 regulates transcription of genes involved in differentiation of HSCs; Regulation of endogenous retroelements by KRAB-ZFP proteins; Regulation of endogenous retroelements by Piwi-interacting RNAs (piRNAs); Regulation of endogenous retroelements by the Human Silencing Hub (HUSH) complex; SIRT1 negatively regulates rRNA expression; Transcriptional regulation by small RNAs
Chromatin organization: CHD1 and CHD2 subfamily; CHD6, CHD7, CHD8, CHD9 subfamily; ChAHP complex assembly; HATs acetylate histones; HDACs deacetylate histones; Interaction of NuRD complexes with transcription factors; NuRD complex assembly
DNA Repair: Cleavage of the damaged purine; Cleavage of the damaged pyrimidine; Nonhomologous End-Joining (NHEJ); Processing of DNA double-strand break ends; Recognition and association of DNA glycosylase with site containing an affected purine; Recognition and association of DNA glycosylase with site containing an affected pyrimidine; Recruitment and ATM-mediated phosphorylation of repair and signaling proteins at DNA double strand breaks
Cell Cycle: Condensation of Prophase Chromosomes; Deposition of new CENPA-containing nucleosomes at the centromere; G2/M DNA damage checkpoint; Inhibition of DNA recombination at telomere; Packaging Of Telomere Ends
Developmental Biology: Activation of anterior HOX genes in hindbrain development during early embryogenesis; Chromatin modifications during the maternal to zygotic transition (MZT); Replacement of protamines by nucleosomes in the male pronucleus; Transcriptional regulation of granulopoiesis
Disease: Defective pyroptosis; Dengue Virus-Host Interactions
and 18 more pathways
Gene Ontology:
Molecular function: protein binding; DNA binding; structural constituent of chromatin; protein heterodimerization activity
Biological process: antibacterial humoral response; antimicrobial humoral immune response mediated by antimicrobial peptide; chromatin organization; innate immune response in mucosa; nucleosome assembly
Cellular component: chromosome, telomeric region; nucleus; nucleoplasm; nucleosome; chromosome
Genetic constraint (gnomAD): Loss-of-function variants: 8 observed, 6.34 expected, observed/expected ratio (o/e) 1.26, 90% interval 0.72 to 1.88. That is too few expected variants to judge how well the gene tolerates losing a copy. Missense variants: 222 observed, 174.7 expected, observed/expected ratio (o/e) 1.27, 90% interval 1.14 to 1.42. Synonymous variants: 122 observed, 71.28 expected, observed/expected ratio (o/e) 1.71, 90% interval 1.47 to 1.94.
Homologues: Orthologues: chimpanzee H2BC3 (100% identical), dog H2BC3 (100% identical), rabbit H2BC3 (100% identical), guinea pig H2BC3 (99% identical). Paralogues in human: H2BC15 (98% identical), H2BC21 (98% identical), H2BC10 (98% identical), H2BC11 (98% identical), H2BC17 (98% identical), H2BC4 (98% identical), H2BC5 (98% identical), H2BC6 (98% identical), H2BC7 (98% identical), H2BC8 (98% identical), H2BC12 (97% identical), H2BC14 (97% identical), and 9 more.
Diseases named in the same sentence as H2BC3 in open-access papers:
H2BC3 is named in the same sentence as 11 diseases in open-access papers, as found by Europe PMC text mining. Sharing a sentence is not in itself a finding about the gene and the disease.
H2BC3 shares sentences with these, for which no sentence is quoted: cancer (5 papers); osteosarcoma (2); breast carcinoma (1); Hyperammonemia (1); melanoma (1); ovarian carcinoma (1); schizophrenia (1); serous carcinoma (1); systemic lupus erythematosus (1); tumor (1); Zika virus infection (1).